STAT3 (signal transducer and activator of transcription 3)
Diseases named in the same sentence as STAT3 in open-access papers (continued):
Sharing a sentence is not in itself a finding about the gene and the disease.
glioblastoma (continued). "Following its physiologic function in brain development and differentiation, our findings indicate that the STAT3 pathway is hijacked by glioblastoma cells and used as a switch for the GSCs to maintain their plasticity, which is fundamental to therapeutic resistance, tumor progression, and relapse." (PMID 33986188, 2021). "As such, miR-21 deregulation is an operational mechanism in both GIMs and glioblastoma cells that modulates multiple oncogenic molecules, and signaling pathway such as STAT3 and anti-miR-21 strategies could be therapeutically developed." (PMID 34532286, 2021). "STAT3 is a key regulator of the aggressive mesenchymal glioblastoma subtype." (PMID 34959661, 2021). "Additionally, glioblastoma (GBM)-derived IL-6/STAT3 signaling pathway correlated with myeloid PD-L1 expression." (PMID 34088360, 2021). "Furthermore, GBP2 is highly upregulated in human glioblastoma and enhances the invasive ability of glioblastoma via the GBP-2/Stat3/FN1 signal cascade." (PMID 34026364, 2021). "Additionally, similar to atovaquone and pyrimethamine in our models, the STAT3 inhibitor JSI-124 leads to activation of the NF-kB pathway in glioblastoma cells." (PMID 33374980, 2020). "A study investigated the impact of cardamonin on glioblastoma stem cells, and examined its effect on apoptosis and self-renewal and whether its activity is related to the STAT3 pathway in this cancer cell population." (PMID 32545187, 2020). "Collectively, ODZ10117 is a promising therapeutic candidate for glioblastoma by targeting STAT3." (PMID 32183406, 2020). "Signal transducer and activator of transcription 3 (STAT3) is highly expressed and overactivated in many tumors, including glioblastoma; thus, targeting STAT3 could be a promising strategy for glioblastoma therapy." (PMID 33256086, 2020). "Here, we demonstrated the therapeutic efficacy of ODZ10117 in glioblastoma by targeting STAT3." (PMID 32183406, 2020). "Moreover, the transcriptional activity of the VEGF promoter in glioblastoma cells can be synergistically activated by STAT3 and Sp1 (Loeffler, Fayard, Weis, & Weissenberger, 2005)." (PMID 32144747, 2020). "Likewise, the phosphorylated levels of STAT3 in glioblastoma multiforme cells treated with cucurbitacin I were greatly decreased." (PMID 32545187, 2020). "In conclusion, the present study has shown that ODZ10117 may be a useful candidate for the STAT3-targeted cancer therapy in glioblastoma." (PMID 32183406, 2020). "We further determined whether ODZ10117 could affect the viability and proliferation of glioblastoma cells because STAT3 regulates the survival and proliferation of cancer cells." (PMID 32183406, 2020). "STAT3 is one of the key target molecules to treat various types of cancers, including glioblastoma." (PMID 32183406, 2020). "In glioblastoma, RCC2 is implicated in tumor proliferation, tumorigenicity, and promoting radio-resistance by activating DNA methyltransferase 1 (DNMT1) transcription in a p-STAT3 dependent manner." (PMID 33521058, 2020). "Our results suggest that STAT3 targeting may be a promising therapeutic strategy in patients with glioblastoma." (PMID 32183406, 2020). "Besides, IL-4 can also abnormally activate STAT3 in glioblastoma (GBM) cells, which are related to the expression of IL-13Rα2." (PMID 33013320, 2020). "Furthermore, 3D tumoursphere assays using glioblastoma cell lines expressing Rac1/2/3 showed increased numbers of tumourspheres (which relate to stem cell numbers) and increased STAT3 activation after IL-6 stimulation." (PMID 32915198, 2020). "In addition, the survival rate was shorter with the higher mRNA level of STAT3 in patients with all brain tumors, astrocytoma, oligodendroglioma, and glioblastoma." (PMID 32183406, 2020).
glioblastoma (continued). "Recently, STAT3 silencing by aptamer-siRNA chimera obtained excellent inhibition in the therapy of glioblastoma, suggesting that the improved oligonucleotides might offer translational potential for the treatment of solid tumors." (PMID 32972405, 2020). "Similarly, glioblastoma favors the expression of several inhibitory molecules such as signal transducer and activator of transcription 3 (STAT3) and Fas ligand (FasL) which aggravate immune inhibitory signals and promote T-cell apoptosis, respectively." (PMID 33202642, 2020). "EZH2 binds and methylates STAT3 to promote tumorigenicity of glioblastoma." (PMID 32477007, 2020). "Bevacizumab-resistant glioblastomas present with increased MET phosphorylation and increased phosphorylation of MET-activated focal adhesion kinase and STAT3, which suggests a role for MET in features associated with anti-angiogenic therapy resistance both in vitro and in vivo." (PMID 31221203, 2019). "One of the first reports demonstrating that STAT3 can act as a tumor suppressor was shown in glioblastoma multiforme (GBM) where a combination of low Phosphatase and tensin homolog (PTEN) expression and loss of STAT3 in astrocytes increased their tumorigenicity." (PMID 31557897, 2019). "Further investigation of STAT3 function in glioblastoma could thus provide a better understanding of the detailed mechanism of inflammatory factor-induced stemness at this context." (PMID 31300060, 2019). "Also, crosstalk between HIF-1α and STAT3 was reported, in different tumor types, including glioblastoma." (PMID 30621209, 2019). "Elevated levels of Stat3 have been highlighted in various types of cancer, including thyroid cancer, melanoma, prostate cancer, Hodgkins lymphoma, breast cancer, hepatocellular carcinoma and glioblastoma." (PMID 31690341, 2019). "In glioblastoma and liver cancer, curcumin decreases cancer stem cell viability and proliferation by ROS-mediated inhibition of NFκB and signal transducer and activator of transcription 3 (STAT3)." (PMID 31217841, 2019). "In a recent study, the role of BMX-STAT3 in glioblastoma radioresistance was demonstrated, indicating that pharmacological inhibition of BMX-mediated STAT3 activation in combination with radiotherapy effectively suppresses tumor growth in glioblastoma-bearing mice." (PMID 30845764, 2019). "Furthermore, in vitro inhibition of Stat3 activation in glioblastoma resulted in a decrease in the proliferative capacity and an increase in cellular sensitivity to TMZ treatment." (PMID 31690341, 2019). "Furthermore, another study indicated that honokiol induces apoptosis in human glioblastoma cell line U87 through suppressing the phosphorylation of STAT3 (Tyr705), down-regulating survivin, and upregulating cleaved caspase-3 expression." (PMID 31877856, 2019). "Studies showed that TGF-β regulates the cancer stem cell self-renewal and differentiation properties via inducing leukemia inhibitory factor (LIF) and IL-11 activation of the JAK/STAT pathway and STAT3 phosphorylation in glioblastoma and colon cancer, respectively." (PMID 30944375, 2019). "We found p-Stat3 Y705 immunopositive cells in 89% of our glioblastoma cases." (PMID 31690341, 2019). "Thus, we added gender, tumour volume, and necrosis, and p-Stat3 Y705 expression status was an independent prognostic factor in glioblastoma (P < 0.001)." (PMID 31690341, 2019). "Overall, these data could open the perspective for future clinical trials using Stat3 inhibitors in glioblastoma." (PMID 31690341, 2019). "p-Stat3 Y705 immunohistochemical expression influences survival in glioblastoma." (PMID 31690341, 2019). "STAT3 is a critical mediator of tumorigenesis, and tumor progression in glioblastoma." (PMID 30123426, 2018). "Moreover, corosolic acid inhibits cell proliferation in glioblastoma cells via suppression of signal transducer and activator of transcription 3 (STAT3) signaling." (PMID 29702597, 2018).
glioblastoma (continued). "STAT3 phosphorylation can suppress radioresistance and improve outcome in glioblastoma stem cells." (PMID 30551687, 2018). "When these VZV data about IL-6/STAT3/ATG5 are considered together with the results from the glioblastoma/autophagy study, we conclude that the elevated levels of IL-6 may also facilitate elevated levels of autophagy in VZV-infected skin explants." (PMID 30568636, 2018). "STAT3 activation in glioblastoma is a poor prognostic factor for tumor growth and survival rate." (PMID 30551687, 2018). "Indeed, STAT3 is a major actor of cell survival after therapy by regulating the expression of anti-apoptotic genes such as Bcl-xL or Mcl-1 in glioblastoma." (PMID 29423098, 2018). "Both MGMT and STAT3 have been shown to mediate TMZ resistance in glioblastoma." (PMID 29949238, 2018). "EZH2 is able to methylate STAT3 to enhance its activity in glioblastoma stem cells." (PMID 29930752, 2018). "Combined specific and unspecific inhibition of STAT3 might represent a promising new strategy in the treatment of glioblastoma." (PMID 28030813, 2017). "While this could complicate therapeutic targeting of STAT3 in glioblastoma, it does provide further evidence that similar signaling and epigenetic mechanisms that govern both cancer stem cells and tissue stem cells at least in this case." (PMID 28384648, 2017). "Recent studies have shown that in glioblastoma models STAT3 and PTEN activities, or lack thereof, may cooperate in modulating tumorigenesis and disease progression." (PMID 28220839, 2017). "STAT3 is a transcription factor that is activated by many cytokines and growth factors, and has a demonstrated role in oncogenesis of many human tumors including glioblastoma." (PMID 28384648, 2017). "Furthermore, IL-6-induced activation of STAT3 have been wildly reported to promote invasion and migration in U251-MG and U87-MG glioblastoma cells." (PMID 28891967, 2017). "The constitutive activation of STAT3 in various brain cancers, including glioblastoma may result from aberrant upstream signaling or defective negative regulation." (PMID 28346397, 2017). "A study has shown that BMX could maintain self-renewal and tumorigenic potential of glioblastoma stem cells by activating STAT3." (PMID 28422715, 2017). "What's more, EZH2 could upregulate STAT3 activity by methylating STAT3, leading to glioblastoma stem-like cells (GSCs) formation, further to sustain the stemness of GSCs." (PMID 27880940, 2017). "Furthermore, STAT3 is required for proliferation and maintenance of multipotency in glioblastoma stem cells." (PMID 28877265, 2017). "STAT3 has been shown to associate with the retinoic acid receptor (RAR), so we considered the possibility that NCoR repression is involved in regulating Jmjd3 in glioblastoma stem cells." (PMID 28384648, 2017). "In addition, we demonstrate a positive correlation between ATF3 and phosphorylation of STAT3 and the inhibition of nuclear translocation of NFκB in glioblastoma cells." (PMID 28250971, 2017). "However, the fact that constitutive Jmjd3 expression substantially inhibits neurosphere formation as well as proliferation indicates that Jmjd3 repression by STAT3 is required for glioblastoma stem cell maintenance in the cell lines tested." (PMID 28384648, 2017). "Interestingly, chromatin immunoprecipitation assays in HT-1080 cells demonstrated that PIBF binds the promoter regions of IL-6, an overexpressed cytokine in glioblastomas that acts as a ligand of the JAK2/STAT3 pathway." (PMID 28168193, 2017). "In addition to in vitro glioblastoma cells, we also observed co-localization of BIS and STAT3 in human glioblastoma tissue." (PMID 27145367, 2016). "Additionally, IL6 siRNA against endogenous IL6 also blocked activation of the IL6-p-STAT3 pathway and hypoxia-induced autophagy in glioblastoma cells." (PMID 27163161, 2016).
glioblastoma (continued). "A series of recent reports demonstrated that constitutive activation of STAT3 in glioblastoma, as well as concomitant activation of various upstream signals involving epidermal growth factor receptor, specific methyltransferase, or PI3 kinase, is regarded as an important regulator of GSC stemness." (PMID 27145367, 2016). "It should be noted though that EZH2 activity has also been associated with transcriptional activation of oncogenic signaling pathways associated with CSC survival and proliferation such as Wnt signaling in colorectal cancer, NOTCH1 and TGFβ1 in prostate cancer, and STAT3 pathway in glioblastoma." (PMID 27793053, 2016). "Finally, glioblastoma stem cells require STAT3 for proliferation and maintenance of multipotency, and loss of the AR yields STAT3 activation." (PMID 26880966, 2016). "Moreover, CD9-silenced glioblastoma stem cells showed altered activation patterns of the Akt, MapK and Stat3 signaling transducers." (PMID 26573230, 2016). "In summary, the present study demonstrated that BIS depletion suppressed the stemness phenotypes associated with glioblastoma cells as evidenced by decreases in the sphere-forming activity and the expression of stemness- and EMT-related genes, likely following STAT3 destabilization." (PMID 27145367, 2016). "Similarly, AKT1 phosphorylates EZH2 and induces the expression of STAT3 in glioblastoma with stem-like cells promoting tumorigenicity." (PMID 27793053, 2016). "Interestingly, 14-3-3ζ can interact with p-STAT3 (Ser-727) and regulates its constitutive activation in human glioblastoma and myeloma cells." (PMID 27806334, 2016). "Moreover, one of the STAT3 targets analysed in this work, Cyclin D2, has recently been reported to be expressed in glioblastoma TICs and to regulate their growth in vivo." (PMID 26486080, 2015). "STAT3 is required for proliferation and maintenance of multi-potency in glioblastoma stem cells." (PMID 26314961, 2015). "The STAT3 transcription factor is a major intracellular signaling protein and is frequently dysregulated in the mostcommon and lethal brain malignancy in adults, glioblastoma multiforme (GBM)." (PMID 26283544, 2015). "In addition, GRIM-19 has been reported to negatively regulate HIF-1α level in a Stat3-dependent manner in glioblastoma cells." (PMID 25575809, 2015). "In addition, a most recent report showed that FoxM1 drives a feed-forward STAT3-activation signaling loop involved in promoting the self-renewal and tumorigenicity of glioblastoma stem-like cells." (PMID 26334131, 2015). "In addition, EZH2 phosphorylation activates STAT3 signaling via STAT3 methylation and promotes the tumorigenicity of glioblastoma stem-like cells." (PMID 25428914, 2015). "Another analysis of 111 patients with glioblastoma showed that 76.6% of the specimens had a positive staining for phosphorylated STAT3-Tyr705 (pSTAT3Tyr705), and those patients carrying tumors with a strong staining had a shorter survival caused by a more aggressive subtype." (PMID 25268165, 2014). "The first hint that STAT3 may be involved in the aggressiveness of human gliomas was the discovery of an amplified expression of the Interleukin-6 (IL-6) gene in glioblastoma tissue samples and cell lines." (PMID 25268165, 2014). "In the present study, we demonstrate that INPP5F strongly inhibits STAT3 activation by interaction with its coiled-coil domain and inhibits its phosphorylation, by which plays essential role in maintaining glioblastoma cells' phenotype and tumorigenic potential." (PMID 25476455, 2014). "BMX is a regulator of glioblastoma stemness, via activation of the p-STAT3 pathway." (PMID 25549333, 2014). "In addition, the ectopic expression of 14-3-3ζ blocked senescence caused by BIS depletion, which was paralleled with a decrease in insoluble STAT3 in A172 glioblastoma cells." (PMID 25412315, 2014).
glioblastoma (continued). "In addition, another recent study showed that Jak2/STAT3 signaling is essential in the migration, invasion, and tumor progression of EGFRvIII glioblastoma cell lines." (PMID 25162558, 2014). "Interestingly, in vitro, levels of constitutive STAT3 activation vary in cultured glioblastoma cell lines, but most cells show a constitutive expression of the IL-6 cytokine family." (PMID 25268165, 2014). "Thus, like other cancers, constitutive activation of STAT3 is likely to play an important role in the survival and proliferation of glioblastomas." (PMID 23998913, 2013). "Moreover, phosphorylation EZH2 binds to and methylates STAT3, thereby enhancing STAT3 activity, which promotes tumorigenicity of glioblastoma stem-like cells." (PMID 24345883, 2013). "Recently STAT3 has been reported to play a role in glioblastoma stem cells." (PMID 24376586, 2013). "STAT3 is found to be constitutively activated in medulloblastoma, and the level of STAT3 activation in medulloblastoma exceeds that of all other brain tumors examined, including glioblastoma, ependymomas, and astrocytomas." (PMID 22984561, 2012). "Additional reports also link STAT3 to stem cell biology as STAT3 is required to maintain the propagation and pluripotency of normal embryonic stem cells, neural stem cells, and glioblastoma stem cells." (PMID 21052560, 2011). "Our results suggest that LLL12 is a potent STAT3 inhibitor and that it may be a potential therapeutic treatment for medulloblastoma and glioblastoma." (PMID 21526200, 2011). "Human glioblastoma cells were induced to apoptosis by the inhibition of STAT3 with FLLL32." (PMID 20712901, 2010). "We detected the effects of FLLL32 on STAT3 phosphorylation by Western blots with a phospho-Y705-specific STAT3 antibody in a panel of glioblastoma, multiple myeloma, colorectal and liver cancer cell lines known to express high endogenous levels of constitutively activated STAT3." (PMID 20712901, 2010). "In glioblastoma, STAT3 can have opposite functions depending on the genetic background; STAT3 is tumor suppressive in the absence of the tumor suppressor PTEN but is oncogenic upon expression of the oncogenic form of the epidermal growth factor receptor EGFRvIII." (PMID 20737505, 2010). "In this study, we investigated the inhibitory effects of a small molecule compound known as LLL-3, which is a structural analogue of the earlier reported STAT3 inhibitor, STA-21, on the cell viability of human glioblastoma cells, U87, U373, and U251 expressing constitutively activated STAT3." (PMID 19127268, 2009). "Stat3 and activated Akt (phospho-Akt) expression increased with malignancy grade, but did not correlate with proliferation and survival within the category of glioblastomas." (PMID 19421400, 2008). "Moreover, the IL-8/CXCR1/STAT3 pathway is crucial for the maintenance of glioblastoma stem cells." (PMID 40362634, 2025). "In glioblastoma, STAT3 phosphorylation was suppressed through SRGN knockdown; in contrast, STAT3 induced SRGN in nasopharyngeal carcinoma, suggesting a potential positive feedback loop in tumor cells that may also operate in TAMs, thereby sustaining a potent oncogenic signaling circuit." (PMID 41476965, 2025). "In this context, researchers have recently developed cancer cell membrane-cloaked biomimetic nanoparticles for the TD of Signal Transducer and Activator of Transcription 3 (STAT3) siRNA to glioblastoma (GBM)." (PMID 40533746, 2025). "In glioblastoma (GBM) microenvironment, rutin indirectly modulated inflammatory signaling by altering microglial miRNA-125b and STAT3 expression in co-culture with cells of GBM." (PMID 41142938, 2025). "STAT3 activation contributes to multiple oncogenic pathways, including those involved in tumor invasion and resistance mechanisms, which may have implications for perineural glioblastoma as well." (PMID 40427146, 2025). "Thus, we assumed that TSPAN6 might interact with CDK5RAP3 and enhance the progress of glioblastoma via STAT3." (PMID 38725860, 2024).